EGFR (epidermal growth factor receptor)
Diseases named in the same sentence as EGFR in open-access papers (continued):
Sharing a sentence is not in itself a finding about the gene and the disease.
glioblastoma (continued). "Epidermal growth factor receptor (EGFR) and lanthionine synthetase C-like 2 (LanCL2) genes locate in the same amplicon, and co-amplification of EGFR and LANCL2 is frequent in glioblastoma." (PMID 34461927, 2021). "These EGFR-CAR NK-92 cells also significantly reduced tumour growth and extended survival in two orthotopic xenograft models of glioblastoma." (PMID 33923528, 2021). "Recently, we demonstrated the use of nanostructured polymeric brushes conjugated with epidermal growth factor receptor (EGFR) and integrated into a microfluidic channel to enhance specificity towards tumor-derived EVs isolated from glioblastoma (GBM) patients." (PMID 33850163, 2021). "The RTK subgroups G1/EGFR, G2/FGFR3, G5/PDGFRA, and G6/Multi-RTK accounted for roughly two-thirds of the glioblastoma IDH-wild-type cases, indicating a major role of RTKs in the pathogenesis of glioblastoma." (PMID 34572759, 2021). "Consequently, “Glioblastoma, IDH-wildtype” in adults should be diagnosed in the setting of an IDH-wildtype diffuse and astrocytic glioma if there is either microvascular proliferation, or necrosis, or TERT promoter mutation, or EGFR gene amplification, or +7/−10 chromosome copy number changes." (PMID 35008238, 2021). "In both glioblastoma cell lines, depletion of FOS, NFKB inhibitor alpha (NFKBIA) and EGFR resulted in similar basal clonogenic and clonogenic radiation survival compared to Lpd depletion." (PMID 34771501, 2021). "When these neural stem cells were cocultured with glioblastoma cells, secreted TRAIL reduced EGFR activation in the glioblastoma cells." (PMID 34769339, 2021). "Yet, the commonality of EGFR in radiosensitivity induced by knockdown of Lpd and RICTOR indicates that the Lpd-RICTOR-EGFR signaling pathway is a fundamental mechanism in glioblastoma." (PMID 34771501, 2021). "For example, miR-1238 was reported to play a vital role in the treatment of glioblastoma as the fact that miR-1238 mediated the chemoresistance of glioblastoma and CAV1/EGFR was revealed to be the direct target during its functioning." (PMID 34606414, 2021). "We confirmed that transfection with miR-34a resulted in a significant decrease in the protein and mRNA levels of ATM, EGFR, Bcl2, c-Met and UGCG in glioblastoma cells." (PMID 33765907, 2021). "EGFR and HER2 receptors are expressed at high levels in human glioblastomas and other solid tumors and have been chosen as targets for a number of oHSVs engineered with specific scFvs." (PMID 34578259, 2021). "Glioblastoma (GBM), a very aggressive and incurable tumor, often results from constitutive activation of EGFR (epidermal growth factor receptor) and of phosphoinositide 3-kinase (PI3K)." (PMID 33978540, 2021). "Evidence implicating the CTD of EGFR in receptor inhibition appears in numerous biochemical and genetic studies, including the identification of activating deletions in the CTD in glioblastoma patients." (PMID 34610265, 2021). "A nanobody targeted to EGFR and conjugated with the apoptosis-inducing ligand TRAIL (ENb2-TRAIL) has been explored in glioblastoma." (PMID 34769339, 2021). "Alternatively, combined use of an EGFR-targeting fluorophore and 5-ALA together provided better delineation of tumour margins in orthotopic models of glioblastoma, raising the possibility of combined use of complimentary agents in FGS." (PMID 34298721, 2021). "We propose that sub-populations of cells with EGFRvIII, high wt EGFR and subsequent high RCN1 expression are likely to be more tolerant and better adapted to survive sub-optimal growth conditions often observed in the glioblastoma micro-environment." (PMID 33801941, 2021). "In glioblastoma (GBM), CDK5 can amplify EGFR signaling by phosphorylating CRMP2 (collapsin response mediator protein 2) at Ser522, sustaining the pro-proliferation effect on tumor cells." (PMID 35006426, 2021).
glioblastoma (continued). "The cell viability of three glioblastoma cell lines (U87MG, A172, T98G) was studied at 72 h following treatment with EGFR kinase inhibitors combined with enzalutamide (AR antagonist) or as monotherapy." (PMID 34681618, 2021). "Paradoxically, all FGFR-fused glioblastomas shared strong PI3K and MAPK pathway suppression effected by SPRY, DUSP and AKAP12 inhibitors, whereas the FGFR2-TACC2 tumor elicited also EGFR suppression by ERRFI1 upregulation." (PMID 33853673, 2021). "The pathways with the highest p-values were signaling pathways in glioblastoma, pathways regulating PI3K-Akt, Hippo, VEGFA-VEGFR2, Ras, and EGFR signaling (p-values < 10−10)." (PMID 33348918, 2020). "A phase II study of erlotinib 150 mg daily in 13 recurrent glioblastoma patients that were PTEN positive, EGFR positive, and EGFRvIII positive by immunohistochemistry (IHC) was stopped early for lack of efficacy (results published 2014)." (PMID 33187135, 2020). "Then the expression of miR-4731, EGFR, ERK-1,2 and AKT-1,2 in two cell lines of glioblastoma (U-87MG and U-251MG) were evaluated by real-time PCR and compared with the glioblastoma cells transduced with the scramble vector as the control." (PMID 33369441, 2020). "This suggests that up-regulation of miR-4731, which results in EGFR, ERK-1,2 and AKT-1,2 suppresion, decrease the proliferation of glioblastoma cells." (PMID 33369441, 2020). "EGFR-CAR NK cells were strongly cytotoxic, inhibited glioblastoma growth, and prolonged survival in tumor-bearing mice." (PMID 33287875, 2020). "NHE9 is also highly expressed in glioblastoma multiforme (GBM), the most common brain tumour, as endolysosomal pH is critical for epidermal growth factor (EGFR) sorting and turnover." (PMID 33118634, 2020). "To investigate the function of ZNF263 and SIX3 in the context of glioblastoma development, we first treated the phenotypically normal astrocytes (HEB cells) with high doses of EGF to mimic EGFR/MAPK hyperactivation during tumor initiation." (PMID 32051553, 2020). "The epidermal growth factor receptor (EGFR), from the receptor tyrosine kinases (RTKs) family, has crucial roles in Glioblastoma (GBM) development and progression." (PMID 33329751, 2020). "Re-analysis of TCGA glioblastoma RNA-seq unveils previously unreported kinase fusions (KLHL7-BRAF) and a 13% prevalence of EGFR C-terminal truncation." (PMID 32466770, 2020). "In glioblastoma, PDGFR, NGF, IGF-1 and, most essentially EGFR upregulation, mediates the migration of glioblastoma cells into normal brain tissues." (PMID 32276377, 2020). "Mice were immunized with an EGFR-overexpressed glioblastoma cell line, LN229 (LN229/EGFR), after which ELISA was performed using recombinant EGFR." (PMID 32218834, 2020). "In conclusion, the findings of the present study identified miR-4731 reduces EGFR, AKT-1,2 and ERK-1,2 expression in glioblastoma cell lines and induce cell cycle arrest and inhibit cell growth in these cells." (PMID 33369441, 2020). "They applied the designed assay to detect glioblastoma biomarkers CD-pan (CD9, CD63, and CD81), with EGFR, EGFRvIII and GAPDH as control markers, from supernatants of glioblastoma cells." (PMID 33276535, 2020). "Drugs targeting the constitutively active form of RTKs (ex: EGFR) and its downstream MAPK/PI3K signalling pathways, are particularly studied as glioblastoma targeted therapies." (PMID 32792639, 2020). "Pooled CAR-T cells targeting HER2/IL-13Rα2 for glioblastoma (GBM), CD19/CD123 for B-ALL, and EGFR/CD133 have been tested in preclinical studies and showed some benefits as well as some disadvantages." (PMID 33207607, 2020). "In this study, we investigated the regulation of EGFR,ERK-1,2 and AKT expression by miR-4731 and their effects on proliferation, cell cycle transition and invasion in glioblastoma cell lines U-251 and U-87." (PMID 33369441, 2020).
glioblastoma (continued). "We aimed to evaluate the clinical outcomes of molecular glioblastoma (mGBM) as compared to histological GBM (hGBM) and to determine the prognostic impact of TERT mutation, EGFR amplification, and CDKN2A/B deletion on isocitrate dehydrogenase (IDH)-wildtype GBM." (PMID 33235995, 2020). "Frequently altered pathways in cancers involve tyrosine and serine/threonine kinases and relevant receptors, including the epidermal growth factor receptor (EGFR), which alter the regulation of Ras oncogenes overexpressed in glioblastoma." (PMID 32292341, 2020). "Chief among these targets is epidermal growth factor receptor (EGFR), the most commonly altered receptor tyrosine kinase and one of the most common alterations in glioblastoma." (PMID 33187135, 2020). "It has been shown that reduced expression levels of miRNA-7 correlates with high levels of EGFR and upstream genes involved in Akt pathway (such as IRS-1 and IRS-2), leading to inhibition of migration, invasion and proliferation of glioblastoma cells." (PMID 32592373, 2020). "The epidermal growth factor receptor (EGFR) is a major oncogenic driver in glioblastoma (GBM)." (PMID 33142709, 2020). "Recently, we developed a novel anti-EGFR mAb (EMab-17, IgG2a, kappa) by immunizing mice with an EGFR-overexpressing glioblastoma cell line, LN229 (LN229/EGFR)." (PMID 32839411, 2020). "Epidermal growth factor receptor (EGFR), EGFRvIII mutant and platelet derived growth factor receptor (PDGFR) can promote the development and invasion of glioblastoma through the PKA-Dock180 signaling pathway." (PMID 33292604, 2020). "Knockdown of LPP-AS2 decreased expression of EGFR in glioblastoma cells, whereas overexpression of LPP-AS2 elevated EGFR expression." (PMID 32962742, 2020). "Overexpression of the transmembrane protein, epidermal growth factor receptor (EGFR), drives tumour progression in several cancers including breast, lung, glioblastoma and head and neck cancers." (PMID 33143170, 2020). "Another E3 ligase, TRIM11, also regulates EGFR levels and TRIM11 expression correlated closely with glioblastoma stem cell (GSC) markers Nestin and CD133 and promoted tumorsphere formation." (PMID 33324551, 2020). "A patient with recurrent glioblastoma (MGG70R) harboring focal, high-level EGFR amplification received the irreversible EGFR tyrosine kinase inhibitor dacomitinib." (PMID 30644426, 2019). "This protein promotes cell proliferation in glioblastoma and tumor formation through induction of the transcription co-activator with a PDZ-binding motif (TAZ)-mediated EGFR signaling pathway." (PMID 31013819, 2019). "Glioblastoma multiforme cells induce PD-L1 secretion by activation of various receptors such as toll like receptor (TLR), epidermal growth factor receptor (EGFR), interferon alpha receptor (IFNAR), interferon-gamma receptor (IFNGR)." (PMID 31661771, 2019). "Research has also shown that combined suppression of Akt and EGFR with gefitinib and MK2206 induced a switch from autophagy to apoptosis in a mouse glioblastoma model." (PMID 31007847, 2019). "Here, we examined its chemosensitization effects on osimertinib, a third-generation EGFR-TKI with an excellent safety profile, in glioma stem cells (GSCs), which are CSCs of glioblastoma." (PMID 31284441, 2019). "IGFBP2 was previously reported to augment the nuclear accumulation of EGFR and to potentiate STAT3 transactivation via nuclear EGFR signaling pathway in glioblastoma." (PMID 31801484, 2019). "Furthermore, the reason for resistance to EGFR-TKIs in glioblastoma remains unknown." (PMID 31284441, 2019). "Epidermal growth factor receptor (EGFR) signaling is activated in several types of solid cancer, including NSCLC, pancreatic cancer, and glioblastoma." (PMID 31614999, 2019).
glioblastoma (continued). "According to the Cancer Genome Atlas (TCGA) genetic screening, 86% of human glioblastoma samples harbor at least one genetic alteration event in the core RTK pathways, and EGFR, PDGFRα, and MET are most commonly amplified RTKs in glioblastomas." (PMID 31245283, 2019). "In this study, we established a matched pair of glioblastoma stem-like cell (GSC) cultures from patient glioblastoma samples before and after epidermal growth factor receptor (EGFR)-targeted therapy." (PMID 30644426, 2019). "Targeted approaches for inhibiting epidermal growth factor receptor (EGFR) and other receptor tyrosine kinases (RTKs) in glioblastoma (GBM) have led to therapeutic resistance and little clinical benefit, raising the need for the development of alternative strategies." (PMID 32642659, 2019). "For example, higher Sema3C levels in castration-resistant prostate cancer cells as well as in glioblastoma U87, bladder T24, and kidney Caki-2 cells activated phosphorylation of MET and EGFR, in a dose-dependent manner." (PMID 31726800, 2019). "The oncogene EGFR is located on chromosome 7, which frequently has CNV gains in IDH-wildtype glioblastomas (∼70%)." (PMID 32082376, 2019). "Levels of EGFR and MET expression in glioblastomas were inversely correlated (Spearman R = -0.59, p < 0.0001)." (PMID 31747973, 2019). "However, it was suggested that treatment of glioblastoma patients with anti-EGFR antibody increases the radiation effect, but this is expected to be most likely an influence on the antibody-exposed vasculature and thus an indirect cancer cell EGFR-independent influence." (PMID 31013819, 2019). "Epidermal Growth Factor Receptor (EGFR), a receptor tyrosine kinase and member of the ERBB family, is overexpressed in cancers including glioblastoma, head and neck, bladder, non-small cell lung, and breast." (PMID 29464085, 2018). "Inhibition of both EGFR and PDGFR is essential for eliminating kinase pathway activity in glioblastomas with mixed cell types." (PMID 30374421, 2018). "As shown for human glioblastoma (GBM) cells, the transactivator property of PKM2 mediates crosstalk between EGFR and β-catenin signaling." (PMID 29991493, 2018). "For glioblastoma IGFBP2, EGFR_pY1068, HER2_pY1248, Caveolin-1, Akt_pT308, Fibronectin, Collagen_VI, and EGFR_pY1173 are decreased in the group of mutated cases." (PMID 30442178, 2018). "The tumor promoting potential of MVP is based on MVP-mediated stabilization of the epidermal growth factor receptor (EGFR)/phosphatidyl-inositol-3-kinase (PI3K)-mediated migration and survival pathways in human glioblastoma multiform cells." (PMID 29038587, 2017). "EGFRvIII, a deletion mutant of the epidermal growth factor receptor (EGFR), is such a specific tumor RNA which is considered to be present in 30% of glioblastoma tumors." (PMID 28681241, 2017). "We examined the cell-to-cell distribution of EGFR and PDGFRA protein expression in glioblastoma derived lines of different genotypes by dual FACS." (PMID 28831081, 2017). "Further, two other bispecific CD16a-based tumor targeting antibodies are in preclinical phase development, i.e., AFM22 and AFM24 that bind to EGFRvIII expressed by several solid tumors, including glioblastoma (GBM), and wild-type EGFR, respectively." (PMID 28620386, 2017). "Missense mutations (R108K, T263P, A289V and G598V; R84K, T239P, A265V, and G574V in mature EGFR) in the extracellular domain of EGFR were also found in GBM and glioblastoma cell lines, which conferred anchorage-independent growth and tumorigenicity upon NIH 3T3 cells." (PMID 28574446, 2017). "In primary glioblastoma multiforme (GBM) tissues, miR-200c and E-cadherin were found to be downregulated when epidermal growth factor receptor (EGFR) was highly amplified." (PMID 29029445, 2017).
glioblastoma (continued). "High-level focal amplifications of EGFR, PDGFRA, and CDK4 were detected in affected glioblastoma samples." (PMID 28638988, 2017). "HET0016 is also shown to decrease MAPK signaling, pSTAT1, EGFR, and HIF-1α in glioblastoma (GBM) tumor lysates." (PMID 29292756, 2017). "Immunodeficient mice received cortical implants of the human glioblastoma cell line, U87MG, modified to express the constitutively-active EGFR mutant, EGFRvIII, GFP and luciferase." (PMID 28394918, 2017). "In glioblastoma and esophageal squamous cell carcinoma, GBP1 upregulation via the EGFR signaling pathway contributes to tumor proliferation and migration both in vitro and in vivo." (PMID 29115931, 2017). "Our previous results have shown that HIF1α regulates the PDK1/ EGFR interaction in the mitochondria and transcriptionally regulates PDK1 in glioblastoma." (PMID 28410193, 2017). "A recent classification of gliomas was based on mutations present in specific genes; in particular, an integrated genomic analysis identified clinically relevant subtypes of glioblastoma, characterized by abnormalities in PDGFRA, IDH1, EGFR and NF1." (PMID 29261132, 2017). "Here the authors show that the importin RanBP6 acts as a tumor suppressor in Glioblastoma and regulates EGFR signalling through promoting translocation of STAT3 to the nuclei and repressing EGFR transcription." (PMID 29229958, 2017). "A number of signalling pathways that include autocrine components, such as TGFalpha/EGF/EGFR, PDGF/PDGFR, HGF/SF and CXCL12/CXCR4 ligand/receptor systems, have been identified in glioma and glioblastoma." (PMID 29149169, 2017). "For example, suppression of miRNA-9 by mutant EGFR signaling resulted in up-regulation of FOXP1 and enhanced glioblastoma tumorigenicity." (PMID 28060761, 2017). "Pharmacological inhibition of EGFR and PDK with DCA was reported recently to inhibit xenograft tumor growth in a variety of carcinoma and glioblastoma cancer cell lines." (PMID 28410193, 2017). "Other dual-therapy regimens being examined are combined inhibition of AKT/mTOR and MDM2 in glioblastoma, and combined c-MET and EGFR in non-small lung cancer." (PMID 26955870, 2016). "We previously characterized the role of miR-7-5p as a tumor suppressor and inhibitor of epidermal growth factor receptor (EGFR) expression and signaling in lung, glioblastoma, breast and head and neck cancers." (PMID 27203220, 2016). "Dual-specific NK cells that recognize both EGFR and EGFRvIII antigens are superior to the monospecific CAR-NK cells in the therapy of glioblastoma." (PMID 27891129, 2016). "Constitutively active mutant versions of receptor tyrosine kinases (RTKs), e.g. EGFR (EGFRvIII), PDGFRA or MET (METΔ7–8), are commonly encountered in primary glioblastomas." (PMID 27586084, 2016). "EGFR amplification mainly occurs in 1p/19q intact, IDH wild type gliomas and indicates the diagnosis glioblastoma." (PMID 25943885, 2015). "Those genes include EGFR, PDGFRA, FGFR3, PIK3CA, MDM4, CDKN2A/B, PTEN and are all members of the core alterated pathways in glioblastoma controlling key phenotypes such as proliferation, apoptosis and angiogenesis." (PMID 25679508, 2015). "Collectively, our data suggest that CD151-α3β1 integrin complexes and EGFR converge at FAK and Graf (ARHGAR26) to drive the motility and invasiveness of glioblastoma." (PMID 26377974, 2015). "In glioblastomas, the membrane receptor DCBLD2 has recently shown to be a key mediator of the enhancement of (EGFR-stimulated) AKT signaling activity." (PMID 25885672, 2015). "The EGFR TKI erlotinib, in particular, has been extensively tested in EGFRvIII expressing glioblastoma, but the results are inconsistent." (PMID 25658924, 2015).